L3MBTL1 (L3MBTL histone methyl-lysine binding protein 1)
Description:
Polycomb group (PcG) protein that specifically recognizes and binds mono- and dimethyllysine residues on target proteins, thereby acting as a 'reader' of a network of post-translational modifications. PcG proteins maintain the transcriptionally repressive state of genes: acts as a chromatin compaction factor by recognizing and binding mono- and dimethylated histone H1b/H1-4 at 'Lys-26' (H1bK26me1 and H1bK26me2) and histone H4 at 'Lys-20' (H4K20me1 and H4K20me2), leading to condense chromatin and repress transcription. Also recognizes and binds RB1/RB monomethylated at 'Lys-860'. Participates in the ETV6-mediated repression. Probably plays a role in cell proliferation. Overexpression induces multinucleated cells, suggesting that it is required to accomplish normal mitosis.
Synonyms: H-l(3)mbt; KIAA0681; L3MBTL; ZC2HC3; dJ138B7.3; DKFZp586P1522
Tractability: Small molecule: a structure with a bound ligand is known; a high-quality ligand is known; it belongs to a druggable protein family. PROTAC: UniProt records ubiquitination sites on it; a small molecule that binds it is known.
Target class: Methyl-lysine/arginine binding protein; MBT domain; Epigenetic regulator; Reader
Gene: Protein-coding gene on chromosome 20 (43,489,442 to 43,550,954, forward strand). Ensembl gene ENSG00000185513.
Subcellular location: Nucleus
Subcellular location (Human Protein Atlas): Nucleoplasm; Midbody ring; Nuclear bodies
Gene Ontology:
Molecular function: chromatin binding; histone binding; histone H1 reader activity; histone H1K26me1 reader activity; histone H1K26me2 reader activity; histone H4K20me2 reader activity; identical protein binding; nucleosome binding; protein binding; SAM domain binding; zinc ion binding
Biological process: chromatin organization; constitutive heterochromatin formation; hemopoiesis; heterochromatin formation; negative regulation of DNA-templated transcription; regulation of megakaryocyte differentiation; regulation of mitotic nuclear division; regulation of cell cycle; regulation of DNA-templated transcription
Cellular component: chromatin; chromatin lock complex; condensed chromosome; nuclear body; nucleolus; nucleoplasm; nucleus
Genetic constraint (gnomAD): Loss-of-function variants: 67 observed, 97.76 expected, observed/expected ratio (o/e) 0.69, 90% interval 0.56 to 0.84. The upper end of that interval is the gene's LOEUF score, 0.84, which puts it in group 3 of 6, group 1 being the genes least tolerant of losing a copy. Missense variants: 1,063 observed, 1,146.1 expected, observed/expected ratio (o/e) 0.93, 90% interval 0.88 to 0.98. Synonymous variants: 450 observed, 442.94 expected, observed/expected ratio (o/e) 1.02, 90% interval 0.94 to 1.1.
Homologues: Orthologues: chimpanzee L3MBTL1 (97% identical), macaque L3MBTL1 (92% identical), dog L3MBTL1 (87% identical), pig L3MBTL1 (84% identical), guinea pig L3MBTL1 (81% identical), mouse L3mbtl1 (76% identical), rat L3mbtl1 (75% identical), rabbit L3MBTL1 (52% identical), zebrafish l3mbtl1a (40% identical), tropical clawed frog L3MBTL1 (38% identical), Drosophila melanogaster l(3)mbt (14% identical), Drosophila melanogaster Sfmbt (12% identical), and 2 more. Paralogues in human: L3MBTL3 (35% identical), L3MBTL4 (33% identical), SCML2 (15% identical), SCMH1 (15% identical), SFMBT2 (14% identical), SFMBT1 (14% identical), L3MBTL2 (13% identical), MBTD1 (12% identical), SAMD11 (11% identical), PHC1 (10% identical), PHC3 (10% identical), PHC2 (10% identical), and 6 more.
Diseases named in the same sentence as L3MBTL1 in open-access papers:
L3MBTL1 is named in the same sentence as 21 diseases in open-access papers, as found by Europe PMC text mining. Sharing a sentence is not in itself a finding about the gene and the disease. The quoted sentences say what the papers report.
brain tumor (4 papers, 2006 to 2024). "For example, the Malignant-Brain-Tumor (MBT) domains of human L3MBTL1 compact nucleosomal arrays by recognizing mono and dimethylation of H4K20 and H1bK26." (PMID 23028348, 2012).
Anxiety (2 papers, 2015 to 2019). Intense feelings of nervousness, tension, or panic often arise in response to interpersonal stresses. "While the exact neuronal functions of L3MBTL1 need further investigation, this protein is highly expressed in the mature brain, and mice deficient in L3mbtl1 have decreased anxiety and depressive-like phenotypes in various mood-related behavioral tests." (PMID 30832413, 2019). "L3mbtl1 loss-of-function was associated with significant decreases in depression and and anxiety in some of the behavioral paradigms." (PMID 25849281, 2015). "The ~ 25–30% increase in locomotion after social isolation in L3mbtl1+/+, in comparison to null mutant mice, was significant and may indicate that loss of L3mbtl1 renders mice less susceptible to increased anxiety after certain types of stress." (PMID 25849281, 2015). "The L3mbtl1-/- cohort of the present study exhibited significantly decreased anxiety in the light-dark box paradigm, and after social isolation as stressor, in the open field test." (PMID 25849281, 2015). "Because depression and anxiety spectrum disorders show considerable overlap in terms of diathesis and underlying neurobiology, we next explored the performance of L3mbtl1-/- mice in several anxiety-relevant paradigms." (PMID 25849281, 2015). "The L3mbtl1-/- mice showed a significant decrease in latency to enter the bright chamber in the light-dark box test, indicating decreased anxiety." (PMID 25849281, 2015). "Given that L3mbtl1 mutant mice exhibit subtle alterations in anxiety-related behavior at baseline, we then asked whether cognitive and emotional functions show changes in the context of a stressor such as social isolation by housing mice individually." (PMID 25849281, 2015). "For example, it will be interesting to explore chromatin sites and target genes regulated by L3mbtl1 and other MBT proteins in preclinical models for anxiety and depression." (PMID 25849281, 2015). "Taken together, these findings suggest that L3mbtl1 disruption is followed by subtle anxiolytic and antidepressant-like effects that become manifest in some but not all depression- and anxiety-related paradigms." (PMID 25849281, 2015). "Thus, L3mbtl1-/- showed a specific resilience to social isolation in the open field, but not in other anxiety- and depression-related tests." (PMID 25849281, 2015). "Therefore, we asked whether depression and anxiety-related behaviors are altered in L3mbtl1-/- mice that were kept under normal ‘non-stressed’ group-housing conditions (2–3 sex-matched littermates as cage mates after weaning)." (PMID 25849281, 2015).
leukemia (2 papers, 2018 to 2022). A malignant (clonal) hematologic disorder, involving hematopoietic stem cells and characterized by the presence of primitive or atypical myeloid or lymphoid cells in the bone marrow and the blood. "Interestingly, higher copy number of the imprinted genes L3MBTL1 and SGK2 at 20q13.12 was weakly associated with drug resistance, and their increased expression was associated with resistance to several agents in leukemia tumor samples from the Beat AML study." (PMID 36461044, 2022).
lung carcinoma (2 papers, 2024). "We hypothesized that L3MBTL1 primarily compacts chromatin by combining with H4K20Me2 in EGFR-TKI-acquired drug-resistant lung cancer cells, because 53BP1 did not bind to H4K20Me2, reducing DNA damage after Osimertinib treatment of Osimertinib-resistant cells." (PMID 39231972, 2024).
myeloid malignancies (2 papers, 2010 to 2023). "L3MBTL1 is a TSG implicated in myeloid malignancies, and L3MBTL3 deregulation is associated with neuroblastoma." (PMID 20698951, 2010). "L3MBTL1, a known transcriptional repressor, has been proposed as a TSG gene in myeloid malignancies associated with 20q deletion." (PMID 20698951, 2010).
adenoma (1 paper, 2016). A neoplasm arising from the epithelium. "We identified hypermethylated CpG sites in the following genes: L3MBTL1, NKX6-2, PREX1, TRAF7, PRDM14, and NEFM with the number of CpG sites being 14, 17, 10, 16, 6, and 6, respectively, after pairwise analysis of normal versus adenoma, adenoma versus cancer, and normal versus cancer." (PMID 27688749, 2016).
breast carcinoma (1 paper, 2021). "L3MBTL1 was reported to be associated with breast cancer and myeloid leukemia including AML." (PMID 34441816, 2021).
breast tumor (1 paper, 2010). "L3MBTL1, L3MBTL2 and L3MBTL3 paralogs were not targeted by deletion in our breast tumor set." (PMID 20698951, 2010).
colorectal cancer (1 paper, 2022). A primary or metastatic malignant neoplasm that affects the colon or rectum. "As shown in our present study, L3MBTL1 functions as both a biomarker for colorectal cancer and READ." (PMID 35664306, 2022).
depression (1 paper, 2015). "Both of these tests suggested that L3mbtl1 loss reduced behavioral patterns associated with depression." (PMID 25849281, 2015). "Here, we exposed L3mbtl1 null mutant mice to a wide range of tests exploring cognition and mood-relevant behaviors at baseline and in the context of social isolation, as a stressor to elicit depression-related behavior in susceptible mice." (PMID 25849281, 2015). "Here, we provide a detailed account for a comprehensive behavioral assessment of adult L3mbtl1 null mutant mice exposed to a wide range of behavioral tests at baseline and after single housing as a social isolation stressor eliciting depression-related behavior in susceptible mice." (PMID 25849281, 2015).
malignant brain tumor (1 paper, 2023). "The malignant brain tumor (MBT) family is a large family with L3MBTL1, L3MBTL2, L3MBTL3, L3MBTL4, and other members." (PMID 38201555, 2023).
Obesity (1 paper, 2022). Accumulation of substantial excess body fat. "DNA methylation change of 15 imprinted genes induced by HFD feeding was observed, including Magel2, Ctnna3, Gab1, and L3mbtl1, that are reported to be linked to the pathogenesis of obesity, high cognitive processes in adulthood, circadian machinery, and growth and development of embryos." (PMID 35458198, 2022).
tumor (10 papers, 2016 to 2025). "L3mbtl1 polycomb protein was described as a candidate tumour suppressor in myeloid disorders, and its expression was described as essential for genome stability." (PMID 40275631, 2025). "Tumor growth rate and volume of the L3MBTL1 knockdown group were significantly lower than the control group." (PMID 39231972, 2024). "The sensitivity of tumor cells to Osimertinib was increased by reduced L3MBTL1 expression, whereas L3MBTL1 overexpression increased the resistance." (PMID 39231972, 2024). "In paraffin‐embedded tissue sections, the expression of Ki-67 in tumor tissues of the L3MBTL1 knockdown plus Osimertinib group was significantly lower compared to other groups, while the expression of γ-H2AX and 53BP1 increased." (PMID 39231972, 2024). "The E3 ubiquitin ligase RNF8 is proposed to be able to destroy the competing proteins of H4K20me2, such as the malignant-brain-tumor (MBT) protein L3MBTL1 (L3MBTL1) and JMJD2A at DSBs, to make H4K20me2 accessible to 53BP1." (PMID 35246238, 2022). "The findings suggest that L3MBTL1 knockdown inhibits tumor growth while increasing DNA damage." (PMID 39231972, 2024). "Tumor xenograft models of H1975/AR sh-NC and H1975/AR sh-L3MBTL1 cells were established in nude mice by subcutaneously injecting the cells into the animals’ right flanks to investigate the role of L3MBTL1 in Osimertinib resistance in vivo." (PMID 39231972, 2024). "L3MBTL1 is known to be a potential tumor suppressor gene in Drosophila fly." (PMID 34441816, 2021). "L3MBTL1, a tumor suppressor with high affinity for H4K20me2, can block 53BP1 binding at DSBs25,43." (PMID 29018219, 2017). "L3MBTL1 gene located on chromosome 20q12 is a tumor suppressor gene." (PMID 27688749, 2016). "Many SGK2 isoforms were not expressed in a large number of AML, breast, ovarian, PDAC, and SCLC cell lines, as compared to a much smaller number of L3MBTL1 isoforms that were not expressed in these tumor histologies." (PMID 40414875, 2025).
cancer (5 papers, 2010 to 2021). A tumor composed of atypical neoplastic, often pleomorphic cells that invade other tissues. "Based on our study, it is conceivable that L3MBTL1 or CoREST play a role in the repression of cancer testis antigens." (PMID 22570633, 2012). "Here we identified specific CpG sites in L3MBTL1, NKX6-2, PREX1, TRAF7, PRDM14,and NEFM as primarily methylated in cancer specimens but not in other colonic lesions; these genes were also found to be implicated in many important pathways relevant to neoplastic transformation." (PMID 27688749, 2016).
psychiatric disorder (1 paper, 2015). A disorder characterized by behavioral and/or psychological abnormalities, often accompanied by physical symptoms. "Therefore, the present findings implicating L3mbtl1 in the control of mood and behavior warrant further investigation to explore the therapeutic potential of this histone methyl-reader protein in psychiatric disorders." (PMID 25849281, 2015).
L3MBTL1 also shares sentences with these, for which no sentence is quoted: atopic asthma (1 paper); hepatocellular carcinoma (1); lung adenocarcinoma (1); myeloid leukemia (1); myeloproliferative neoplasm (1); neuroblastoma (1).